MIR4430 (microRNA 4430)
Synonyms: hsa-mir-4430
Gene: MicroRNA gene on chromosome 2 (33,418,516 to 33,418,564, forward strand). Ensembl gene ENSG00000283591.
Diseases named in the same sentence as MIR4430 in open-access papers:
MIR4430 is named in the same sentence as 1 disease in open-access papers, as found by Europe PMC text mining. Sharing a sentence is not in itself a finding about the gene and the disease. The quoted sentences say what the papers report.
COVID-19 (1 paper, 2022). A disease caused by infection with severe acute respiratory syndrome coronavirus 2. "Interestingly, one of the top upregulated transcripts after Rem treatment is MIR4430, a hardly characterized microRNA that however was recently associated with other repurposed drugs to combat COVID-19 in an in silico study." (PMID 35686037, 2022).